IGSF1 (immunoglobulin superfamily member 1)
Description:
Seems to be a coreceptor in inhibin signaling, but seems not to be a high-affinity inhibin receptor. Antagonizes activin A signaling in the presence or absence of inhibin B (By similarity). Necessary to mediate a specific antagonistic effect of inhibin B on activin-stimulated transcription.
Synonyms: InhBP; IGDC1; KIAA0364; PGSF2; IGCD1; MGC75490; CHTE; p120
Tractability: Antibody: UniProt places it where antibodies can reach, with high confidence; UniProt predicts a signal peptide or a membrane-spanning region; its Gene Ontology location is reachable by antibodies, with medium confidence.
Gene: Protein-coding gene on chromosome X (131,273,506 to 131,578,899, reverse strand). Ensembl gene ENSG00000147255.
Subcellular location: Membrane (Isoform 1); Membrane (Isoform 2); Secreted (Isoform 3)
Subcellular location (Human Protein Atlas): Cytosol
Gene Ontology:
Molecular function: activin receptor antagonist activity; inhibin binding; protein binding; transmembrane signaling receptor activity
Biological process: negative regulation of activin receptor signaling pathway; regulation of DNA-templated transcription; signal transduction
Cellular component: membrane; plasma membrane; extracellular region
Homologues: Orthologues: chimpanzee IGSF1 (99% identical), macaque IGSF1 (95% identical), rabbit IGSF1 (91% identical), pig IGSF1 (91% identical), dog IGSF1 (91% identical), mouse Igsf1 (86% identical), rat Igsf1 (86% identical), guinea pig IGSF1 (86% identical), tropical clawed frog xilr1 (7% identical). Paralogues in human: LILRA6 (10% identical), LILRB1 (10% identical), LILRB5 (10% identical), LILRB3 (9% identical), LILRA1 (9% identical), LILRA2 (9% identical), KIR3DL2 (9% identical), LILRB2 (9% identical), KIR3DL1 (9% identical), KIR3DL3 (9% identical), LILRA4 (9% identical), OSCAR (9% identical), and 13 more.
Diseases named in the same sentence as IGSF1 in open-access papers:
IGSF1 is named in the same sentence as 38 diseases in open-access papers, as found by Europe PMC text mining. Sharing a sentence is not in itself a finding about the gene and the disease. The quoted sentences say what the papers report.
Central hypothyroidism (26 papers, 2015 to 2025). A type of hypothyroidism due to an insufficient stimulation of an otherwise normal thyroid gland. "The main features of immunoglobulin superfamily, member 1 (IGSF1) deficiency are central hypothyroidism and macroorchidism." (PMID 40162297, 2025). "In particular, IGSF1 deficiency, caused by loss-of-function IGSF1 mutations, is characterized by central hypothyroidism and macroorchidism, with a few cases showing GHD." (PMID 40868191, 2025). "IGSF1 dysfunction is strongly linked with congenital central hypothyroidism in humans, and this phenotype is recapitulated in mouse models." (PMID 38987241, 2024). "Initially, IGSF1 variants were only reported in patients with central hypothyroidism (CeH) and macroorchidism." (PMID 35456429, 2022). "Inactivating mutations in both these genes have been implicated in the etiology of congenital central hypothyroidism, and the IGSF1 deficiency that is more prevalent and better characterized has been shown to induce hypoprolactinemia and GH hypersecretion." (PMID 35978432, 2022). "For instance, loss-of-function mutations in IGSF1 result in an X-linked syndrome of central hypothyroidism and testicular enlargement." (PMID 33150070, 2020). "Human loss-of-function mutations in IGSF1 cause central hypothyroidism, hypoprolactinemia, and macroorchidism." (PMID 31650157, 2020). "Loss-of-function mutations of IGSF1 are an X-linked cause of central hypothyroidism (CeH) and hypoprolactinemia." (PMID 31448769, 2020). "Although further validation is required to substantiate this proposed model, these observations support a candidate modulatory mechanism for central hypothyroidism in IGSF1 deficiency." (PMID 31650157, 2020). "Loss-of-function mutations in a member of the immunoglobulin superfamily, Immunoglobulin superfamily member 1 (IGSF1), have been identified in patients with X-linked central hypothyroidism." (PMID 29730183, 2018). "In conclusion, two relevant molecular mechanisms linked to central hypothyroidism and macroorchidism in IGSF1 deficiency are identified, revealing IGSF1 as an important regulator of TGFβ/Activin pathways in the pituitary." (PMID 28262687, 2017). "In summary, we revealed here two distinct molecular effects of IGSF1 consistent with the development of central hypothyroidism and testicular enlargement in IGSF1 deficiency." (PMID 28262687, 2017). "Mutations in the immunoglobulin superfamily, member 1 gene (IGSF1/Igsf1) cause an X-linked form of central hypothyroidism." (PMID 28686733, 2017). "IGSF1 deficiency represents the most common genetic cause of central hypothyroidism and is associated with multiple other characteristics." (PMID 26840047, 2016). "Central hypothyroidism remains the key feature of IGSF1 deficiency, being present in all male cases." (PMID 26840047, 2016). "In the present case, IGSF1 deficiency was diagnosed at the age of 19 years, based on a history of transient GH deficiency, persistent central hypothyroidism, and hypoprolactinemia, and the finding of macro-orchidism." (PMID 26757742, 2016). "Loss‐of‐function mutations in another member of this superfamily, IGSF1, were recently identified in patients with X‐linked central hypothyroidism." (PMID 27137492, 2016). "Immunoglobulin super family member 1 (IGSF1) deficiency syndrome is characterized by central hypothyroidism, delayed surge in testosterone during puberty, macro-orchidism, and in some cases, hypoprolactinemia and/or transient growth hormone (GH) deficiency." (PMID 26757742, 2016). "Loss of function mutations in IGSF1 causes central hypothyroidism in humans and mice." (PMID 38987241, 2024). "Mutations in the IGSF1 gene cause congenital central hypothyroidism in humans." (PMID 35653309, 2022). "Similarly, IGSF1 (leads to central hypothyroidism), SFTA3 and GLIS3, whose mutations are linked to CH, were identified." (PMID 34249923, 2021).
Central hypothyroidism (continued). "X-linked, loss-of-function mutations in IGSF1 result in a variable spectrum of anterior pituitary dysfunction, which is most pronounced in affected males, resulting almost universally in mild to moderate congenital central hypothyroidism (CCeH)." (PMID 31650157, 2020). "However, in 2012 a study of 11 families with central congenital hypothyroidism identified a novel X-linked cause of central hypothyroidism, IGSF1." (PMID 29026407, 2017). "In addition to central hypothyroidism, males carrying an inactivating mutation of IGSF1 manifest a clinical syndrome that includes macro-orchidism (88% of patients) and variable hypoprolactinemia (60% of patients)." (PMID 29026407, 2017). "Importantly, although the IGSF1 deficiency syndrome is X-linked, 18% of female mutation carriers have central hypothyroidism, about 20% have biochemical prolactin deficiency (although lactation is apparently normal), and up to one-third have late menarche." (PMID 29026407, 2017). "IGSF1 (Immunoglobulin Superfamily 1) gene defects cause central hypothyroidism and macroorchidism." (PMID 28262687, 2017). "Male children with an idiopathic combined GH, PRL, and TSH deficiency, showing persistent central hypothyroidism but transient GH deficiency upon retesting at adult height, should be screened for mutations in the IGSF1 gene, especially when macro-orchidism and/or hypoprolactinemia are present." (PMID 26757742, 2016). "Male children with an idiopathic combined GH and TSH deficiency, showing a persistent central hypothyroidism but a transient GH deficiency, should be screened for loss-of-function mutations or deletions of the IGSF1 gene, especially when delayed puberty and macro-orchidism are present." (PMID 26757742, 2016). "Mutations in the immunoglobulin superfamily, member 1 (IGSF1) gene cause the X-linked IGSF1 deficiency syndrome consisting of central hypothyroidism, delayed pubertal testosterone rise, adult macroorchidism, variable prolactin deficiency, and occasionally transient partial GH deficiency." (PMID 26840047, 2016). "Hitherto, studies of the endocrine effects of IGSF1 deficiency may been confounded by selection bias, with gene screening being undertaken predominantly in cases of central hypothyroidism." (PMID 26416826, 2015). "Prospective follow up of patients with IGSF1 mutations will help define the natural history of the disease, addressing questions such as whether central hypothyroidism can evolve in carrier females." (PMID 26416826, 2015). "Additionally, phenotyping of female IGSF1 mutation carriers indicated that although IGSF1 deficiency is X-linked, one-third of heterozygous females exhibit central hypothyroidism, and up to 11% demonstrate hypoprolactinaemia." (PMID 26416826, 2015). "Murine studies have suggested that impaired TRH signaling may play a role in the central hypothyroidism associated with IGSF1 deficiency." (PMID 26416826, 2015). "Thus, both in vitro and in vivo evidence suggest that IGSF1 deficiency may cause central hypothyroidism by impairing expression and downstream signaling of the TRH receptor in pituitary thyrotropes." (PMID 29026407, 2017). "We advise genetic evaluation of all patients with central hypothyroidism of unknown cause for IGSF1 mutations, especially when accompanied by an X-linked inheritance pattern, prolactin or GH deficiency, disharmonious pubertal development, macroorchidism, or delayed adrenarche." (PMID 26840047, 2016). "TRH-induced TSH secretion is correspondingly impaired in Igsf1 knockout mice, likely explaining their central hypothyroidism." (PMID 35653309, 2022). "The five genes associated with isolated congenital central hypothyroidism are thyrotropin-releasing hormone receptor gene (TRHR), thyroid-stimulating hormone β-subunit gene (TSHB), and the more recently described genes IGSF1, TBL1X, and IRS4." (PMID 33585976, 2021).
Central hypothyroidism (continued). "Isolated congenital central hypothyroidism (CeH) can result from mutations in TRHR, TSHB, and IGSF1, but its etiology often remains unexplained." (PMID 27603907, 2016). "Reports of families with TRHR or IGSF1 mutations also highlight the fact that family screening following diagnosis in a young proband, may identify apparently healthy first, second or third-generation family members with hitherto undiagnosed central hypothyroidism." (PMID 26416826, 2015). "In conclusion, nearly half a century after the first report on an enigmatic association of congenital nystagmus and central hypothyroidism, we identified a male newborn with the same association and a Xq26 deletion encompassing FRMD7 and IGSF1." (PMID 25780367, 2015). "In addition, human loss-of-function mutations in the immunoglobulin superfamily member 1 (IGSF1) gene cause X-linked IGSF1 deficiency syndrome, consisting of central hypothyroidism, hypoprolactinemia, adult macro-orchidism, and excess GH." (PMID 39356415, 2024). "Recently, two studies have begun to elucidate the role of IGSF1 in the HPT axis and a potential mechanism by which it may cause central hypothyroidism." (PMID 29026407, 2017). "Up to now, systematic IGSF1 mutation analysis has not been performed in larger cohorts of patients with transient or persistent GH deficiency in combination with central hypothyroidism and low PRL levels." (PMID 26757742, 2016). "Isolated central hypothyroidism is a rare entity, with an estimated incidence of 1:65 000 and known genetic causes affect the TSH biosynthetic pathway, comprising mutations in TSHB and TRHR, and IGSF1." (PMID 26416826, 2015). "Absence of IGSF1 may permit excessive TGFβ-mediated suppression of TRHR that leads to central hypothyroidism." (PMID 29026407, 2017). "Therefore, pituitaries harboring IGSF1 defects may not synthesize enough TRHR, leading to a type of central hypothyroidism combining low TSH synthesis and bioactivity." (PMID 28262687, 2017).
Macroorchidism (11 papers, 2016 to 2025). The presence of abnormally large testes. "Pathogenic variants in IGSF1 were first described in patients with CeH who were noted to have macroorchidism." (PMID 40162297, 2025). "Other studies have shown a possible association between an IGSF1 mutation and neurological phenotypes; however, other phenotypic consequences were also observed within the affected family, including macroorchidism and infertility." (PMID 36017582, 2022). "Common human variation in IGSF1 is associated with age at menarche, and loss-of function mutations cause a human syndrome of congenital hypothyroidism, macroorchidism, Prolactin and Growth Hormone deficiency, delayed pubertal testosterone and obesity." (PMID 27503363, 2016). "Although macroorchidism may results from IGSF1 loss-of-function in testes, other Igsf1 knock-out animal models need to be explored in order to further elucidate its underlying pathophysiological mechanism." (PMID 34566885, 2021). "We show that IGSF1 is strongly expressed in gonadotropes of the young adult male rat enabling the “pituitary pathogenic hypothesis” for macroorchidism." (PMID 28262687, 2017). "We present here morphological, clinical and molecular evidence strongly indicating that a pituitary disorder may be an important pathogenic mechanism leading to macroorchidism in IGSF1 deficiency." (PMID 28262687, 2017). "Loss-of-Function (LOF) mutations in the IGSF1 gene have been reported to cause the X-linked IGSF1 deficiency syndrome, a rare genetic condition that primarily affects males, characterized by hypothyroidism, macroorchidism, delayed puberty, obesity, and infertility." (PMID 41462822, 2025). "Mutations in both IGSF1 and TBL1X can lead to X-linked isolated CeH, but IGSF1 mutations are also associated with low PRL, variable GH deficiency, metabolic syndrome, and postpubertal macroorchidism." (PMID 34093435, 2021). "Based on a patient with a full deletion of IGSF1 clinically followed from neonate to adulthood, we investigated a common pituitary origin for hypothyroidism and macroorchidism, and the role of IGSF1 as regulator of pituitary hormone secretion." (PMID 28262687, 2017). "Later on, IGSF1 variants were also reported in patients with additional endocrinopathies, sometimes without macroorchidism." (PMID 35456429, 2022). "Subsequently, the clinical features of patients with IGSF1 pathogenic variants have expanded and include delayed puberty, hypoprolactinemia, transient partial growth hormone (GH) deficiency, and increased body mass index (BMI), with or without macroorchidism." (PMID 40162297, 2025). "Notably, the proband does not present with macroorchidism, a feature typically associated with IGSF1 deficiency." (PMID 41462822, 2025). "Therefore, a major derangement of pituitary gonadotropes (and not hypothyroidism) seems here to be a distinct factor involved in macroorchidism in the absence of IGSF1." (PMID 28262687, 2017).
hypothyroidism (9 papers, 2014 to 2025). Abnormally low levels of thyroid hormone. "While mouse models have successfully recapitulated the IGSF1 deficiency central hypothyroidism phenotype, they lack the testicular enlargement phenotype." (PMID 34566885, 2021). "In particular, hypothyroidism and delayed puberty associated with IGSF1 loss of function may predominantly increase fat mass proportions, thereby negating some of the effects of GH excess on body composition." (PMID 31650157, 2020). "Most humans with hemizygous IGSF1 mutations exhibit biochemical hypothyroidism that is comparable to biallelic TRHR mutation cases, comprising mild-moderate CCH with detectable TSH and apparently normal neurological development even when the diagnosis is delayed until adulthood." (PMID 26416826, 2015). "Another recently identified feature of patients with IGSF1 pathogenic variants and demonstrated in this case is development of MASLD, likely due to obesity or suboptimally treated hypothyroidism." (PMID 40162297, 2025). "Compared to isolated forms of central CH due to IGSF1, TBL1X and IRS4 variants, FT4 concentrations in PSIS patients are usually lower and classify as moderate severe hypothyroidism." (PMID 34566885, 2021). "This suggests prenatal, non-recoverable damage of brain development by in utero hypothyroidism in severe cases of IGSF1 deficiency." (PMID 28262687, 2017). "Secondary hypothyroidism is much less frequent, either with isolated TSH deficiency due to mutations inactivating the TSH β-subunit, the TRH receptor, or IGSF1 (ImmunoGlobulin SuperFamily member 1), or more commonly with TSH deficiency associated with other pituitary hormone deficiencies." (PMID 24446653, 2014).
central congenital hypothyroidism (4 papers, 2017 to 2021). Central or secondary congenital hypothyroidism is a type of permanent congenital hypothyroidism characterized by permanent thyroid hormone deficiency that is present from birth and secondary to a disorder in the thyroid-stimulating hormone (TSH) - thyrotropin-releasing hormone (TRH) system. "Numerous cases of IGSF1 deficiency have since been described, making it the most common identifiable genetic cause of isolated central congenital hypothyroidism." (PMID 29026407, 2017). "However, a 2012 study of 11 families with central congenital hypothyroidism discovered that loss-of-function mutations in the IGSF1 gene caused an X-linked syndrome of central hypothyroidism." (PMID 33878729, 2021).
congenital hypothyroidism (4 papers, 2016 to 2018). A thyroid hormone deficiency present from birth. "Second, we observed increased birth weight in one-third of patients, in accordance with two of six Japanese cases of IGSF1 deficiency as well as with other causes of congenital hypothyroidism." (PMID 26840047, 2016). "Additionally, birth weight SDS was greater than +2SDS in three of seven evaluable hemizygotes, which is also a recognized feature of congenital hypothyroidism as well as being reported in 25% IGSF1 deficient males." (PMID 30086211, 2018).
Obesity (4 papers, 2016 to 2025). Accumulation of substantial excess body fat. "Of interest, the IRS4 gene is involved in the IGF-1/growth hormone pathway and IGSF1 is associated with human obesity." (PMID 28257443, 2017).
pituitary hormone deficiencies (4 papers, 2014 to 2025). "Loss-of-function variants in IGSF1 result in CeH, either isolated or in combination with additional pituitary hormone deficiencies." (PMID 35456429, 2022). "Variants in immunoglobulin superfamily, member 1 (IGSF1) are the most common genetic cause of central CeH but may cause other pituitary hormone deficiencies." (PMID 40162297, 2025). "Alterations in pituitary development genes as well as mutations of immunoglobulin superfamily member 1 and transducin β-like protein 1 can result in CCH and multiple pituitary hormone deficiencies." (PMID 28515030, 2017).
Anxiety (3 papers, 2016 to 2022). Intense feelings of nervousness, tension, or panic often arise in response to interpersonal stresses. "For instance, a haplotype with a coding variant of IGSF1 that is strongly associated with anxiety and fear traits across breeds and has an allele frequency of 0.18 in pet Labradors14 was homozygous non-risk in the present cohort." (PMID 36056154, 2022). "Lastly, X chromosome locus markers near IGSF1 are associated with fear, anxiety, aggression and body size traits, and markers near HS6ST2 are associated with sociability." (PMID 35130840, 2022).
Azoospermia (1 paper, 2022). Absence of any measurable level of sperm,whereby spermatozoa cannot be observed even after centrifugation of the semen pellet. "This indicates that the rare variants identified in this study within the IGSF1 gene may also be closely related to azoospermia phenotype." (PMID 36017582, 2022).
breast tumors (1 paper, 2015). "Interestingly, some of the negative regulators of activin signaling pathway such as follistatin, β-glycan, IGSF1, and IGSF10 showed downregulation in breast tumors compared with normal samples." (PMID 28721365, 2015).